MIER1 (MIER1 transcriptional regulator)
Description:
Transcriptional repressor regulating the expression of a number of genes including SP1 target genes. Probably functions through recruitment of HDAC1 a histone deacetylase involved in chromatin silencing.
Synonyms: Er1; Mi-er1; hMi-er1; KIAA1610
Tractability: PROTAC: UniProt records ubiquitination sites on it; ubiquitination databases record sites on it; its protein half-life has been measured.
Gene: Protein-coding gene on chromosome 1 (66,924,895 to 66,988,619, forward strand). Ensembl gene ENSG00000198160.
Subcellular location: Nucleus (Isoform 1); Nucleus (Isoform 2); Nucleus (Isoform 3); Cytoplasm (Isoform 4); Cytoplasm (Isoform 5); Cytoplasm (Isoform 6)
Subcellular location (Human Protein Atlas): Nucleoplasm
Gene Ontology:
Molecular function: histone deacetylase activity; histone deacetylase binding; protein binding; transcription corepressor activity
Biological process: chromatin remodeling; positive regulation of canonical NF-kappaB signal transduction; regulation of DNA-templated transcription; negative regulation of transcription by RNA polymerase II
Cellular component: histone deacetylase complex; nucleoplasm; nucleus; protein-containing complex; transcription repressor complex; cytoplasm
Genetic constraint (gnomAD): Loss-of-function variants: 22 observed, 37.18 expected, observed/expected ratio (o/e) 0.59, 90% interval 0.42 to 0.85. The upper end of that interval is the gene's LOEUF score, 0.85, which puts it in group 3 of 6, group 1 being the genes least tolerant of losing a copy. Missense variants: 355 observed, 427.3 expected, observed/expected ratio (o/e) 0.83, 90% interval 0.76 to 0.91. Synonymous variants: 142 observed, 138.53 expected, observed/expected ratio (o/e) 1.03, 90% interval 0.89 to 1.18.
Homologues: Orthologues: chimpanzee MIER1 (100% identical), pig MIER1 (97% identical), rabbit MIER1 (95% identical), dog MIER1 (93% identical), rat Mier1 (93% identical), macaque MIER1 (92% identical), mouse Mier1 (86% identical), guinea pig MIER1 (80% identical), tropical clawed frog mier1 (68% identical), zebrafish mier1b (52% identical), zebrafish mier1a (46% identical), Caenorhabditis elegans T07F8.4 (21% identical), and 2 more. Paralogues in human: MIER3 (40% identical), MIER2 (32% identical), MTA2 (16% identical), MTA1 (16% identical), MTA3 (15% identical).
Diseases named in the same sentence as MIER1 in open-access papers:
MIER1 is named in the same sentence as 26 diseases in open-access papers, as found by Europe PMC text mining. Sharing a sentence is not in itself a finding about the gene and the disease. The quoted sentences say what the papers report.
breast carcinoma (17 papers, 2008 to 2025). "A shift from nuclear to cytoplasmic localization of MIER1 during breast cancer progression has been observed, suggesting that nuclear MIER1 contributes to the repression of genes involved in invasive breast carcinoma." (PMID 26938916, 2016).
leukemia (1 paper, 2014). A malignant (clonal) hematologic disorder, involving hematopoietic stem cells and characterized by the presence of primitive or atypical myeloid or lymphoid cells in the bone marrow and the blood. "Although, these are relatively understudied genes, PRELP and MIER1, both are associated with leukemia." (PMID 24947164, 2014).
liver steatosis (1 paper, 2023). "Importantly, the lipids-EIF2S1-MIER1 pathway is impaired in animals with chronic liver steatosis; whereas MIER1 depletion significantly improves regeneration in these animals." (PMID 36934083, 2023). "Interestingly, we showed that MIER1 was physiologically regulated by acute liver steatosis in liver regeneration via acute stress-induced translational control." (PMID 36934083, 2023). "In the meantime, high-fat diet (HFD)-fed and aging animals with chronic liver steatosis showed no response to the acute stress posed by the temporary lipid accumulation, and thus had impaired MIER1 regulation; whereas loss of MIER1 greatly improved liver regenerative capacity in these animals." (PMID 36934083, 2023).
nephritis (1 paper, 2008). Inflammation of renal tissue. "Although Mier1 expression and Hdac1 functions in B cells are not well characterized, Hdac1 is ubiquitously expressed in lymphoid tissues, and Hdac inhibitors have been used to induce cell cycle arrest and downregulate inflammatory cytokines and nephritis in MRL/lpr lupus mice." (PMID 19578517, 2008).
steatosis (1 paper, 2023). Increased lipid within the cytoplasm of cells. "Our previous studies suggest the function of the early phase acute steatosis in promoting liver regeneration via MIER1 regulation." (PMID 36934083, 2023). "We thus next wanted to further assess that it is the acute steatosis during liver regeneration that causes ISR and hence the reduction of MIER1 protein synthesis in vivo." (PMID 36934083, 2023). "Besides MIER1, several other genes have also been identified that were under translational control induced by steatosis, although their functional contribution to liver regeneration remains unknown." (PMID 36934083, 2023).
Stroke (1 paper, 2023). Sudden impairment of blood flow to a part of the brain due to occlusion or rupture of an artery to the brain. "MIER1, a transcriptional repressor, and RMI1, a DNA repair protein, were also positively correlated with stroke severity." (PMID 36803375, 2023).
tumor (6 papers, 2012 to 2024). "Initial studies showed that total MIER1 mRNA levels were increased in breast carcinoma cell lines and tumour samples; in a more recent study, no consistent difference in MIER1alpha protein expression levels between normal breast and tumour samples was detected." (PMID 24812577, 2012).
infection (2 papers, 2020 to 2021). The state of being infected such as from the introduction of a foreign agent such as serum, vaccine, antigenic substance or organism. "For instance, the observed expression changes of several transcriptional regulators including MIER1, which regulates the transcription of many SP1 target genes, may in part explain the predominantly observed decrease in protein expression on infection." (PMID 32591346, 2020).
MIER1 also shares sentences with these, for which no sentence is quoted: cancer (5 papers); endometriosis (3); breast tumors (2); prostate carcinoma (2); acute myocardial infarction (1); bladder cancer (1); colorectal cancer (1); endometrial cancer (1); gastric cancer (1); invasive breast carcinoma (1); ischemic heart disease (1); liver fibrosis (1); lung adenocarcinoma (1); melanoma (1); Miscarriage (1); ovarian carcinoma (1); prostatic tumors (1); triple-negative breast carcinoma (1).